ZEB1 (zinc finger E-box binding homeobox 1)
Diseases named in the same sentence as ZEB1 in open-access papers (continued):
Sharing a sentence is not in itself a finding about the gene and the disease.
melanoma (continued). "Our work shows that mutated BRAF melanoma patients with high levels of ZEB1 expression may not benefit from MAPKi treatment and that ZEB1 could serve as a predictive marker in order to stratify BRAF‐mutated melanoma into MAPKi‐sensitive and MAPKi‐resistant subgroups." (PMID 27596438, 2016). "During melanoma progression, EMT-inducing transcription factors (Snail1, Twist1, ZEB1 and Slug) are regulated by BRAF/MEK/ERK (MAPK) and PI3K signaling." (PMID 26517521, 2016). "Normal epidermal melanocytes from a melanoma patient expressed low ZEB1 and high ZEB2 expression, whereas the melanoma cells at deep sites from the same patient had high ZEB1 and low ZEB2 levels." (PMID 25763355, 2015). "The cordycepin treatment downregulated the expression of ZEB1, HMGA2 and TWIST1 by more than 50% but had minimal effects on ADAM9, RAC1, SALL4, CTNNB1, ZEB2 and YES1 in these two melanoma cell lines." (PMID 25868853, 2015). "Induction of ZEB1 and SNAIL family members as discussed by Vandamme and Berx, as well as repression of E-cadherin is observed during melanoma progression." (PMID 25763355, 2015). "We also found that melanoma migration and invasiveness was mediated by miR-33b though directly targeting high mobility group AT-hook 2 (HMGA2), Twist1 and human zinc finger E-box binding homeobox 1 (ZEB1)." (PMID 25868853, 2015). "Based on human melanoma samples, a switch from ZEB2/SLUG to ZEB1/TWIST expression indicates malignant progression." (PMID 25538895, 2014). "ZEB1 impairs the recruitment of immune cells into the TME by downregulating CXCL10 production, which is necessary for T cells to enter the tumor and attack melanoma cells." (PMID 40872475, 2025). "Targeting ZEB1 may be a promising strategy that promotes CD8+ T cell recruitment within tumors and increases immunotherapeutic responses in melanoma." (PMID 40097979, 2025). "Linear correlation and statistical significance (p < 0.05) between ZEB1 and FSTL1 were observed in cervical cancer (CESC), esophageal cancer (ESCA), head and neck cancer (HNSC), lung squamous cell carcinoma (LUSC), melanoma (SKCM), and sun-exposed/unexposed skin." (PMID 38605354, 2024). "ZEB1’s ectopic expression is thus sufficient to repress the secretion of T-cell-attracting chemokines, leading to the impairment of CD8+ T cell recruitment and melanoma immune evasion." (PMID 38398085, 2024). "Zeb1 mRNA levels were similarly expressed in A375 and BLM melanoma cells." (PMID 38247872, 2024). "This technique enables the specific quantification of the level of expression of markers of melanoma cell state in ZEB1-expressing melanoma cells, and excludes other cells from the microenvironment." (PMID 38519642, 2024). "Interestingly, while some ZEB1 peaks were conserved in MDA-MB-231, peaks in ZEB2, SOX10 and NGFR were only found in melanoma cells." (PMID 38519642, 2024). "In the present study, we did not specifically elucidate how an EMT-like phenotype or VM was induced by a lack of APJ in B16 melanoma cells, although Zeb1 expression was apparently induced." (PMID 36776217, 2023). "Notably, ZEB1 increases the expression of NCSC markers, such as NGFR, a major regulator of phenotype switching in melanoma." (PMID 35432344, 2022). "In the melanoma FTMs, RFs did not affect ZEB1 expression but clearly induced ZEB2 protein expression at the ingrowth areas compared to the PFs." (PMID 36232952, 2022). "In addition, the expression of the zinc finger E-box-binding homeobox 1 (ZEB1), a transcription factor that accelerates migration and invasion, indicates epithelial–mesenchymal transition (EMT) in canine melanoma cells." (PMID 36077992, 2022). "Our team demonstrated that ZEB2 and SNAIL2 are highly expressed in MITFhigh proliferative melanoma cells, whereas decreased expression of ZEB2 and SNAIL2 and aberrant activation of ZEB1 and TWIST1 promoted phenotype switching towards an invasive, dedifferentiated and MITFlow phenotype." (PMID 35432344, 2022).
melanoma (continued). "We next examined ZEB1 and PKC-θ expression in CD8+ T cells isolated from liquid biopsies of metastatic stage IV melanoma patients stratified based on RECIST v1.1 into responder, primary resistance, or secondary resistance (resistant after an initial positive response to immunotherapy)." (PMID 35326747, 2022). "Indeed, we observed changes in important EMT markers and regulators such as ZEB1, CDH1 (E-Cadherin), CDH2 (N-Cadherin), SNAI2, and TGFß1 in the MITF-KO cells as well as in TCGA melanoma samples." (PMID 33438577, 2021). "Once established, this invasive melanoma signature is then stabilised via GLI1 and ZEB1 signalling." (PMID 32796736, 2020). "Analyzing specific genes involved in phenotypic plasticity, the TCGA dataset confirmed the direct and significant correlation between expression levels of molecules connected to EMT (ZEB1) and stemness (YAP1, ABCC4) molecules, as well as NAMPT in melanoma patients." (PMID 33419372, 2020). "Finally, we will overview the current literature on ZEB1 and ZEB2 in the melanoma context and link this to the ‘phenotype-switching’ model of melanoma cellular plasticity." (PMID 32796736, 2020). "Moreover, intra-tumor heterogeneity was observed within human primary melanoma lesions by immunohistochemical analyses: opposite gradients in the expression of ZEB2/SNAIL2 and TWIST1/ZEB1 were observed from superficial to deep sites." (PMID 32759677, 2020). "This intrinsic balance between ZEB1 and ZEB2 could prove to be a promising therapeutic target for melanoma patients." (PMID 32796736, 2020). "Finally, the AM404 + GSK126 combination, after O/N treatment, reversed the EMT-like profile of melanoma cells by reducing SNAIL, ZEB1, AXL, and α-catulin protein expression while upregulating MITF and E-cadherin." (PMID 30710146, 2019). "The miR-200 family, moreover, is considered of particular relevance for the metastatic process of melanoma cells, since it drives the EMT process by negatively influencing the zinc finger E-box-binding homeobox 1 (ZEB1) and E-Cadherin, while stimulating the expression of N-Cadherin and vimentin." (PMID 31861757, 2019). "In melanomas, genes coordinately expressed with GPC6 were largely those involved in cell adhesion and migration including INHBA, PDGFC, PDGFRA, PPAP2B, SPRX2, TCF4, and TNFAIP6 and ZEB1." (PMID 31199813, 2019). "In addition, it can suggest the possible role of OVOS2 in the EMT process of melanoma cells; however, further study with the detections of additional markers of EMT, such as Snail, Twist, and Zeb1, would give more evidences." (PMID 29684087, 2018). "Analyses of the expression of the neural crest cell marker p75/CD271, another melanoma‐initiating cell marker, by Western blot and Q‐PCR, consistently revealed its upregulation in A375 and SKMEL5 cells that overexpressed ZEB1." (PMID 27596438, 2016). "Several transcription factors, including ZEB1/2, SNAIL1/2, TWIST1/2, MITF and JUN, have been shown to play key roles in melanoma EMP-like processes; however, the mechanisms by which internal and micro-environmental signals are integrated to modulate transcriptional activity are not fully understood." (PMID 27852308, 2016). "The protein levels of the FRA1 transcription factor, a known inducer of ZEB1 in melanomas, also increased, whereas TWIST1 was not affected." (PMID 27596438, 2016). "While our study was mainly focused on ZEB1, TWIST1 is also frequently activated in melanoma." (PMID 27596438, 2016). "Furthermore, in order to evaluate the therapeutic potentials of PDGFD, ZEB1, and THRB, we obtained 413 melanoma samples with clinical information and gene expression from TCGA." (PMID 25537510, 2015). "In line with this, immunohistochemical analysis of melanomas showing signs of hypoxia identified a FN1highMITFlow subpopulation expressing presumed melanoma cancer-stem cell markers such as ABCB5, HIF2A, JARID1B, and NGFR as well as ZEB1 and SNAIL." (PMID 25538895, 2014).
melanoma (continued). "We found that ZEB1 knockdown may correspond to reduced tumorigenicity and EMT change of B16F10 cells as well as melanoma metastases in vivo mouse model." (PMID 24625224, 2014). "The recent work on EMT-inducing transcription factors in melanoma leads to the idea that melanoma cells cycle between a differentiated and state (high levels of ZEB2 and SLUG) and a oncogenic invasive phenotype (high levels ZEB1 and TWIST)." (PMID 25538895, 2014). "Here, we show that the tumor vaccine B16F10/GPI-IL-21 in combination with potentially synergistic active therapies, such as either miR200c overexpression or ZEB1 knockdown, significantly represses tumor growth, blocks melanoma EMT program and inhibits tumor metastasis in a murine melanoma model." (PMID 24625224, 2014). "Furthermore, MITF−/low melanoma cells strongly expressed the Nerve Growth Factor Receptor (NGFR/CD271) identified as a marker of MICs and, partially, the epithelial-to-mesenchymal transition (EMT) marker ZEB1." (PMID 38191367, 2024). "Simple Western analysis was performed to confirm PLK1 overexpression in melanoma cells and its effect on EMT markers, which showed an increasing trend in the expression of mesenchymal markers, such as N-cadherin and Vimentin, as well as transcription factors ZEB1 and SNAIL." (PMID 38184733, 2024). "Indeed, only male melanoma cells showed a significant reduction of E-cadherin and an increased expression of N-cadherin and Zeb1, while in female melanoma cells none of the EMT markers significantly changed." (PMID 36499700, 2022). "Using a proximity ligation assay, which detects close interactions between two target proteins, PKC-θ was shown to exist in proximity to ZEB1 in the nuclei of immunotherapy-resistant PD-1+/CD8+ T cells but not immunotherapy-responsive T cells derived from melanoma patients." (PMID 35326747, 2022). "Overall, our data demonstrate that PKC-θ is enriched in dysfunctional PD1+/CD8+ T cells derived from resistant melanoma patients and that, in dysfunctional PD1+/CD8+ T cells, PKC-θ forms a nuclear complex with ZEB1 that may potentially drive the CD8+ T-cell exhaustion phenotype." (PMID 35326747, 2022). "Therefore, Fra-1 inhibition might counteract the intrinsic or acquired melanoma resistance to BRAF and/or MEK inhibitors, by suppressing the ZEB1-regulated EMT-like transcriptional programs." (PMID 35326630, 2022). "While different studies used ZEB2 and ZEB1 as additional markers to define the proliferative (MITFhigh/AXLlow) or invasive (MITFlow/AXLhigh) phenotypes, respectively, our data further demonstrated that EMT-TFs are major regulators of melanoma cell plasticity that fuel intra-tumor heterogeneity." (PMID 32759677, 2020). "Indeed, ZEB1 and TWIST1 have been shown to downregulate MITF whereas SNAIL2 or ZEB2 induce MITF expression, demonstrating that these EMT-TFs act as key players in melanoma phenotype switching." (PMID 32858889, 2020). "Silencing of c-Myc by siRNA in three different melanoma cell lines, or treatment of melanoma cells with the c-Myc inhibitor 10058-F4 downregulated FOXM1, EZH2, and H3K27me3, as well as the EMT-related markers ZEB1, N- Cadherin, α-catulin and SNAIL, but upregulated E-Cadherin." (PMID 30710146, 2019). "However, in ZEB1low/MITFhigh established melanoma cell lines, such as 501MEL, ZEB1 overexpression was not sufficient to promote p75 expression, even upon PLX4032 treatment." (PMID 27596438, 2016). "Interestingly, a significant proportion of ZEB1‐negative melanoma samples from patients with primary resistance displayed strong TWIST1 staining." (PMID 27596438, 2016). "However, unlike epithelial cancers, in melanoma ZEB1 and ZEB2 are reported to be differentially expressed in alternate phenotypic states." (PMID 25763355, 2015).
melanoma (continued). "To augment therapeutic B16F10 melanoma efficacy by tumor vaccine B16F10/ GPI-IL-21 in C57BL/6 mice, we adopted a novel strategy that the tumor vaccine B16F10/GPI-IL-21 were combined with miR200c overexpression or ZEB1 knockdown in B16F10 cells in current antitumor experiment." (PMID 24625224, 2014). "Indeed, ZEB1/TWIST1 are expressed in the bulk of primary melanoma and ZEB1 ectopic expression promotes tumorigenic features in melanoma cell lines, while its knock-down drastically decreases the tumorigenic growth of melanoma cells in vivo upon xenograft in nude mice." (PMID 32759677, 2020). "Therefore, while ZEB1 and TWIST1 harbor oncogenic activities in melanoma, ZEB2 and SNAIL2, which are expressed in normal melanocytes and are required for their proper differentiation, they may act as oncosuppressive proteins in this specific neural crest-derived lineage." (PMID 32759677, 2020). "However, the link between EMT-TFs and proliferation remains unclear since we did not observe any defect in proliferation upon modulation of ZEB1 expression in melanoma cells." (PMID 32759677, 2020). "Data from cell lines and patients indicate that a subset of mutated BRAF melanomas with high levels of ZEB1 expression may be intrinsically insensitive to BRAFi and MEKi, suggesting that melanoma patients with high levels of ZEB1 expression may not benefit from MAPKi treatment." (PMID 27596438, 2016). "To determine whether the levels of ZEB1 and MITF were predictive of the patients’ response to MAPKi, we performed immunohistochemical staining for ZEB1, MITF but also TWIST1 on a cohort of 70 human BRAFV600 melanoma samples from patients whose response to the treatment was known." (PMID 27596438, 2016). "This is evidenced by the lack of ZEB1 alteration upon p65 silencing, suggesting a distinct, direct regulatory role for KPC1 in controlling melanoma plasticity via ZEB1 that is separate from its impact on NF-κB signaling." (PMID 41429767, 2025). "Thin primary melanomas (such as MM28, Breslow = 0.8 mm) or thick primitive melanomas (such as MM25, Breslow = 16 mm) displayed a proliferative/differentiated ZEB2+ MITF+ SOX10+ phenotype with no or low ZEB1, SOX9 and NGFR expression." (PMID 38519642, 2024). "In contrast, in melanoma cell lines, SNAI1 does not activate the transcription of ZEB1, thus, we have not included this interaction in our model." (PMID 32226439, 2020). "The most significantly enriched melanoma signatures among activated genes were the invasive and the NCSC, while the undifferentiated signature was only partly induced, suggesting that ZEB1 is able to promote the expression of some but not all undifferentiated markers." (PMID 38519642, 2024). "Of note, ZEB1 and ZEB2 TF activity could not be reliably assessed based on DoRothEA pan-cancer database, because of melanoma cell-type specificities." (PMID 38519642, 2024). "In B16-F10 mouse melanoma cells, although a 24-h bGH treatment did not significantly increase the EMT markers, at the protein level, we saw a significant increase in ZEB-1." (PMID 33291663, 2020). "NFATc2+ melanomas expressed AXL, N-cadherin and ZEB1, but lacked MITF." (PMID 30710146, 2019). "ZEB1 downregulation in B16-F10 melanoma cells and in its presumed cancer-stem cell CD133+ CD44+ subpopulation reduced their tumor growth in vivo, yet it has not been shown whether lack of ZEB1 effectively depletes the CD133+ CD44+ fraction in B16-F10 tumors as such." (PMID 25538895, 2014).
gastric cancer (140 papers, 2013 to 2025). A primary or metastatic malignant neoplasm involving the stomach. "Gastric cancer tissues with high ZEB1 expression also show an increased risk of peritoneal metastasis." (PMID 39247601, 2024). "In gastric cancer its expression was associated with increased levels of ZEB1 and Wnt pathway, but other works have proposed opposing results in HCC." (PMID 31003545, 2019). "Western-blotting was used to detect the protein expression of EMT/ metastasis related markers MMP-2, MMP-9, N-cadherin, Zeb1, Vimentin, Snail and E-cadherin in gastric cancer cells." (PMID 40265472, 2025). "Unexpectedly, MnSOD treatment induced zinc finger E-box homeobox 1 (ZEB1) expression in SGC7901 gastric cancer cells, which was associated with a poor five-year survival rate and poor prognosis in gastric cancer patients." (PMID 40092690, 2025). "Expression of the DNA endonuclease Mus81 positively correlated with ZEB1 expression in gastric cancer, and Mus81 promotes gastric metastasis by regulating the ZEB1 transcription." (PMID 40092690, 2025). "LAMA4 gene expression is upregulated in gastric-cancer cells through the binding of the ZEB1 (Zinc finger E-box-binding homeobox 1) transcription factor to the LAMA4 promoter." (PMID 38542354, 2024). "Research on ZEB1 in peritoneal metastatic cancer indicates that patients with high expression of ZEB1 in gastric cancer peritoneal lavage fluids have poor prognosis." (PMID 39247601, 2024). "LINC01559 is known to be transcriptionally upregulated by the transcription factor zinc finger E-box binding homeobox 1 (ZEB1) in gastric cancer." (PMID 38311781, 2024). "For example, ILF3‐AS1 has been shown to interact with miR‐200b‐3p, leading to the repression of ZEB1 expression and influencing cell proliferation and metastasis in gastric cancer." (PMID 39135276, 2024). "A gastric cancer stem cell peritoneal metastasis model demonstrated upregulation of ZEB1 through immunofluorescence." (PMID 39247601, 2024). "This phenomenon is in accordance with the fact that indisulam downregulates ZEB1 in gastric tumor samples and high expression of ZEB1 mRNA in gastric cancer tissues deleteriously affects patient survival." (PMID 36805336, 2023). "Immunoblotting analysis uncovered that ZEB1 was expressed higher in gastric cancer tissues than in the paratumor tissues." (PMID 36805336, 2023). "Analyses of patient samples and datasets in public databases reveal that tumor tissues from patients with gastric cancer express high ZEB1 mRNA and this high expression reduces patient survival rate." (PMID 36805336, 2023). "Kaplan–Meier plotter data analyses uncovered that high ZEB1 mRNA expression substantially shortened the overall survival time of patients with gastric cancer." (PMID 36805336, 2023). "Using a cell line–based model, we further demonstrated that indisulam exhibited the inhibitory activity on the migration of gastric cancer cells through reducing ZEB1." (PMID 36805336, 2023). "Nevertheless, based on our work, we can conclude that ZEB1 is, at least, one of the major transcription factors that are responsible for the indisulam-inhibited migration of gastric cancer cells." (PMID 36805336, 2023). "Further, in gastric cancer, an antagonistic relation between ZEB1 and ELF3 was observed through their downstream targets, such as IRF6." (PMID 36864480, 2023). "To further confirm the regulation of indisulam on ZEB1 in gastric cancer tissues, we used different concentrations of indisulam to treat gastric cancer tissues in culture plates." (PMID 36805336, 2023). "Taken together, these data demonstrated that indisulam degraded ZEB1 in patient gastric tumor tissues and high expression of ZEB1 deteriorated the progression of gastric cancer." (PMID 36805336, 2023). "To further explore the role of ZEB1 on the inhibitory effect of indisulam on the migration of gastric cancer cells, we first carried out the scratch assay with AGS and MGC803 cells in which ZEB1 was knocked down by siRNA." (PMID 36805336, 2023).